ENSG00000284931 (novel protein)
Gene: Protein-coding gene on chromosome 11 (5,248,270 to 5,254,783, reverse strand). Ensembl gene ENSG00000284931.
Genetic constraint (gnomAD): Loss-of-function variants: 2 observed, 7.74 expected, observed/expected ratio (o/e) 0.26, 90% interval 0.1 to 0.81. That is too few expected variants to judge how well the gene tolerates losing a copy. Missense variants: 62 observed, 117.08 expected, observed/expected ratio (o/e) 0.53, 90% interval 0.43 to 0.65. Synonymous variants: 22 observed, 43.19 expected, observed/expected ratio (o/e) 0.51, 90% interval 0.36 to 0.73.